UBXN2A (UBX domain protein 2A)
Description:
Acts to repress the ubiquitination and subsequent endoplasmic reticulum-associated degradation of CHRNA3 by the STUB1-VCP-UBXN2A complex in cortical neurons. Also acts to promote the translocation of CHRNA3 to the plasma membrane and subsequently increases plasma membrane acetylcholine-gated ion-channel activation (By similarity). Positively mediates the ubiquitination and proteosomal degradation of RICTOR, may thereby act as a negative regulator of the mTORC2 pathway.
Synonyms: UBXD4
Tractability: PROTAC: UniProt records ubiquitination sites on it; ubiquitination databases record sites on it; its protein half-life has been measured.
Gene: Protein-coding gene on chromosome 2 (23,926,788 to 24,004,909, forward strand). Ensembl gene ENSG00000173960.
Subcellular location: Golgi apparatus; Endoplasmic reticulum; Perikaryon; Cell projection, dendrite; Nucleus; Cytoplasm
Subcellular location (Human Protein Atlas): Centrosome
Gene Ontology:
Molecular function: protein binding; ubiquitin binding; acetylcholine receptor binding
Biological process: negative regulation of ERAD pathway; negative regulation of proteolysis; positive regulation of protein catabolic process; autophagosome assembly; Golgi organization; membrane fusion; nuclear membrane reassembly; proteasome-mediated ubiquitin-dependent protein catabolic process
Cellular component: ATPase complex; cytoplasm; nucleus; cytosol; endoplasmic reticulum; Golgi apparatus; perikaryon; cis-Golgi network; dendrite
Genetic constraint (gnomAD): Loss-of-function variants: 18 observed, 23.8 expected, observed/expected ratio (o/e) 0.76, 90% interval 0.52 to 1.12. The upper end of that interval is the gene's LOEUF score, 1.12, which puts it in group 4 of 6, group 1 being the genes least tolerant of losing a copy. Missense variants: 240 observed, 276.78 expected, observed/expected ratio (o/e) 0.87, 90% interval 0.78 to 0.96. Synonymous variants: 95 observed, 96.37 expected, observed/expected ratio (o/e) 0.99, 90% interval 0.83 to 1.17.
Homologues: Orthologues: chimpanzee UBXN2A (99% identical), macaque UBXN2A (94% identical), dog MFSD2B (88% identical), rabbit UBXN2A (88% identical), rat Ubxn2a (85% identical), pig UBXN2A (85% identical), mouse Ubxn2a (85% identical), guinea pig UBXN2A (82% identical), rat LOC100910099 (81% identical), tropical clawed frog ubxn2a (47% identical), zebrafish ubxn2a (42% identical). Paralogues in human: NSFL1C (36% identical), UBXN2B (33% identical), UBXN11 (22% identical).